FLNC (filamin C)
Diseases named in the same sentence as FLNC in open-access papers (continued):
Sharing a sentence is not in itself a finding about the gene and the disease.
osteoporosis (1 paper, 2022). A condition of reduced bone mass, with decreased cortical thickness and a decrease in the number and size of the trabeculae of cancellous bone (but normal chemical composition), resulting in increased fracture incidence. "After construction the miRNA-gene interaction network, we identified 6 hub miRNAs (hsa-miR-18b-3p, hsa-miR-361-3p, hsa-miR-484, hsa-miR-519e-5p, hsa-miR-940, and hsa-miR-1275) and 6 hub genes (THBS1, IFNAR2, ARHGAP5, TUBB2B, FLNC, and NTF3) for osteoporosis." (PMID 35757478, 2022). "And in our study, for the first time, the intimate association of the other 3 miRNAs (hsa-miR-18b-3p and hsa-miR-519e-5p) and 4 genes (IFNAR2, ARHGAP5, FLNC, and NTF3) with osteoporosis was discovered." (PMID 35757478, 2022).
osteosarcoma (1 paper, 2021). A usually aggressive malignant bone-forming mesenchymal neoplasm, predominantly affecting adolescents and young adults. "In our study, the p-filamin-C level in rhIL-6- and lobaplatin-treated osteosarcoma cells, which are resistant to lobaplatin as described in a previous study, was higher than that in cells treated with lobaplatin alone." (PMID 34717622, 2021). "Among the identified phosphoproteins, p-filamin-C exhibited the second-highest level in the osteosarcoma cells treated with rhIL-6 prior to lobaplatin compared with those treated with lobaplatin alone." (PMID 34717622, 2021). "p-FLNC, AKT1, and MAPK signaling contributes to resistance to lobaplatin in osteosarcoma SaOS-2 cells and may represent molecular targets to overcome osteosarcoma chemoresistance." (PMID 34717622, 2021). "The immunohistochemical staining results showed that p-FLNC, AKT1 and p-ERK1/2 were highly expressed in platinum-resistant clinical specimens but weakly expressed in platinum-sensitive specimens, and platinum-resistant osteosarcoma specimens demonstrated weak expression of p-JNK." (PMID 34717622, 2021).
rectal cancer (1 paper, 2025). A primary or metastatic malignant neoplasm that affects the rectum. "In this study, we identified four molecular markers (MYLK, FLNC, MYH11, and NEXN) as potential prognostic biomarkers for rectal cancer for the first time." (PMID 39762799, 2025).
Respiratory insufficiency (1 paper, 2014). "Respiratory insufficiency has been described in association with the p.Trp2710X mutation in FLNC, and frequently was the cause of death, but never the initial symptom." (PMID 25208129, 2014).
sudden cardiac death (1 paper, 2024). "A mutation in the genes for lamin A/C (LMNA), desmoplakin (DSP) producing gene, sodium voltage-gated channel alpha subunit 5 (SCN5A) gene, and filamin C (FLNC) are genetic markers associated with DCMs that caused a higher risk in sudden cardiac death (SCD) related to malignant arrhythmias." (PMID 38975458, 2024).
Tetralogy of Fallot (1 paper, 2025). A congenital cardiac malformation comprising pulmonary stenosis, overriding aorta, ventricular septum defect, and right ventricular hypertrophy. "Here, we report a novel truncating FLNC variant (NM_001458.5:c.1453C>T, p.Q485 *) in a family with two fetuses affected by Tetralogy of Fallot (TOF), a congenital heart defect not previously associated with FLNC variants." (PMID 41464097, 2025). "Notably, FLNC has not been implicated in structural defects such as Tetralogy of Fallot (TOF) to date." (PMID 41464097, 2025).
myopathies (38 papers, 2008 to 2025). "The FLNC gene encoding filamin C is primarily associated with myopathies and arrhythmogenic cardiomyopathies." (PMID 40487118, 2025). "FLNC variants were first associated with myopathies with excessive intracellular protein aggregate accumulation, the myofibrillar myopathies (MFM) in 2005." (PMID 38397924, 2024). "For example, FLNC, which encodes for filamin C, was originally identified in patients with myofibrillar myopathy presenting with isolated muscle involvement." (PMID 37240454, 2023). "Dominant heterozygous mutations of Filamin C gene cause several forms of myopathy and structural or arrhythmogenic cardiomyopathy." (PMID 35903116, 2022). "Studies of Ldb3Ala165Val/+ mice indicate that the myopathy-associated LDB3 p.Ala165Val mutation triggers early aggregation of filamin C and its chaperones at muscle Z-disc before aggregation of the mutant protein." (PMID 33742095, 2021). "In humans, a wide variety of myopathy-associated mutations and variants have also demonstrated importance of FLNC in muscle development." (PMID 32295012, 2020). "The importance of the FLNC gene was highlighted when it was found to be associated with myofibrillar myopathy in skeletal and cardiac muscles." (PMID 32295012, 2020). "Surprisingly few data are available on FLNc expression levels in myopathy patients with an FLNc mutation." (PMID 32887649, 2020). "In myofibrillar myopathies, mutations in FLNC were reported to destabilize muscle tissue homeostasis via the formation of protein aggregates." (PMID 29073160, 2017). "Filamins are comprised of three homologous proteins—Filamin A, B, C. Human mutations in FLNB have been associated primarily with skeletal anomalies, whereas FLNC mutations cause myopathies." (PMID 29240780, 2017). "In the context of myofibrillar myopathies, mitochondrial pathology has been reported in patients with mutations in filamin-C, myotilin, ZASP, FHL1, plectin, and desmin." (PMID 27393313, 2016). "Functions of FLNC have been demonstrated in muscle tissues, where mutations are responsible for several forms of myopathies." (PMID 25065397, 2014). "We expressed and purified the C-terminal fragment of human FLNC (Uniprot Q14315) containing immunoglobulin-like domains 22–24 (amino acid residues 2403-2725) and three mutants of this construction associated with cardio- and myopathy." (PMID 40564978, 2025). "LDB3 interactors filamin C and myotilin are also expressed in the spinal motor neuron, nerve, and neuromuscular junction, thereby providing the basis for neurogenic manifestations in myopathies associated with mutations in these so-called muscle proteins." (PMID 36609526, 2023). "FLNC is predominantly expressed in skeletal and cardiac muscles and variants in this gene were first involved in the development of dominant distal and myofibrillar myopathies." (PMID 36066120, 2022). "Notably, FLNC is a dosage-sensitive gene and reduced expression of FLNc causes myopathies, indicating that the highly reduced FLNc protein level of our Hom mice is a major mechanism contributing to their phenotype." (PMID 32887649, 2020). "USP25m also interacts with two other sarcomeric proteins, actin α-1 (ACTA1) and filamin C (FLNC), which are two of the three sarcomeric proteins that are essential for muscle maintenance and differentiation and are implicated in the pathogenesis of severe myopathies." (PMID 34249948, 2021). "Notably, mutations in NEB, NRAP, and FLNC have been associated with NM and other myopathies." (PMID 28826497, 2017). "We investigated the interaction of HspB7 and its α-crystallin domain with the wild-type (WT) C-terminal fragment of human filamin C (FLNC), containing immunoglobulin-like domains 22–24 and its three mutants associated with cardio- and myopathies." (PMID 40564978, 2025). "It thus appears that ZAKβ signalling is required for the turnover of certain proteins and those identified here, FLNC, BAG3 and Myotilin, are implicated in myofibrillar myopathies." (PMID 37427997, 2023).
myopathies (continued). "Filamin C-related myofibrillar myopathies (MFM) caused by mutations in the filamin C gene (FLNC) are autosomal dominant inherited and characterized by progressive myopathies that eventually result in wheelchair dependence." (PMID 29866061, 2018). "FLNC has been found to be the interaction protein of HSPB7, and the loss of HSPB7 in skeletal muscles can cause progressive myopathy with FLNC aggregation." (PMID 28827800, 2017). "Despite the less-severe phenotype, HspB7 CKO mutant mice showed a progressive myopathy phenotype with the aggregation and mislocalization of its interacting protein FLNC." (PMID 26929074, 2016). "Collectively, our findings suggest that HSPB7 is essential for maintaining muscle integrity, which is achieved through its interaction with FLNC, in order to prevent the occurrence and progression of myopathy." (PMID 26929074, 2016). "Mutation in MYOT causes MFM3; this type is defined by the accumulation of products coming from myofibril disintegration with characteristic myofibrillar myopathy symptoms, as this protein plays an important role in sarcomere assembly, interacting with filamin C and a-actinin." (PMID 40869293, 2025). "Mutations in DES, CRYAB, FLNC, LDB3, and BAG3 lead to myofibrillar myopathies and/or DCM." (PMID 39684857, 2024). "In addition to LDB3, other rare myopathy gene products such as filamin C and myotilin are expressed in the nervous system [this study; (Mologni13; Xie14)]." (PMID 36609526, 2023). "However, the distal and proximal myopathy-related missense variants in the amino-terminal actin-binding domain of filamin C (FLNC p.Ala193Thr, p.Met251Thr) increased filamin C’s affinity to F-actin, resulting in F-actin aggregates." (PMID 33802723, 2021). "Mutations in filamin C (FLNC), a gene that encodes a protein associated to the Z-disk, have been reported to cause myopathies inherited as a dominant trait that may present with different clinical and histological features." (PMID 29073160, 2017). "On the contrary, missense mutations in the N-terminal actin binding domain of FLNC and the frameshift deletion c.5160delC have been identified in distal myopathies without myofibrillar aggregates." (PMID 29073160, 2017). "In humans, mutations in the actin-binding protein Filamin-C result in myopathies, but the underlying molecular function is not well understood." (PMID 28732005, 2017). "Abnormal localization and expression of FLNC have been detected in numerous myopathies." (PMID 26929074, 2016). "Defects in the FLNC gene coding for an actin-binding protein, are already known to cause myofibrillar myopathies but the gene was supposedly excluded as being involved in the pathogenesis of LGMD1F." (PMID 23414517, 2013). "The first FLNC-related myopathy was reported in 2005 showing that a nonsense mutation (c.G8130A, p.W2710Ter) in the FLNC dimerization domain causes a disease in a large German family characterized by muscle weakness and typical myofibrillar myopathy features." (PMID 32295012, 2020). "However, recessive loss of function mutations in the KY gene also result in mislocalized FLNC expression in patients and mice, indicating that formation of aggregates driven by the mutant protein is not a universal mechanism in myofibrillar myopathies." (PMID 37427997, 2023). "Immunofluorescence analysis of muscle sections from mice and a human biopsy showed evidence of FLNC and BAG3 accumulations as well as other myofibrillar myopathy markers." (PMID 37427997, 2023).
cancer (28 papers, 2012 to 2025). A tumor composed of atypical neoplastic, often pleomorphic cells that invade other tissues. "Variants classified as pathogenic across all five tools were cross-referenced with known cancer genes, identifying high-confidence mutations in FLNC, MAP2K1, and ABCA1." (PMID 41373405, 2025). "Filamin C (FLNC) is a member of actin-binding and cross-linked filament protein family, which promotes the migration and invasion of cancer cells." (PMID 32547947, 2020). "Filamin-C belongs to a family of three actin-binding proteins that stabilize actin networks and connect them to the cell membrane, with its silencing associated with cancer-increased invasiveness through the lamellipodia formation." (PMID 36430209, 2022). "However, a pan‐cancer analysis for the survival association in different tumor entities revealed that FLNC expression was associated with poor prognosis in 16 different types of cancers including NSCLC." (PMID 33934493, 2021). "Among these model genes (FLNC, KLK6, PTGIS, PLAAT1 and GLYATL2), FLNC is an actin-binding protein that regulates the actin cytoskeleton in cells and is involved in cancer metastasis." (PMID 38363409, 2024). "Among them, candidate proteins EEF2, U2AF2 and FLNC are significantly enriched in the three pathways of “spliceosome” (p-value: 1.01 × 10−3), “proteoglycans in cancer” (p-value: 8.58 × 10−2) and “focal adhesion” (p-value: 1.48 × 10−3)." (PMID 34437425, 2021). "Multiple studies report a role for FLNA and FLNB in cancer cell migration, but the role of FLNC remains largely unexplored." (PMID 33934493, 2021). "In contrast to the data obtained, Flnc knock down in cancer cells has been reported to lead to proliferation impairment, and high expression of FLNC is considered as predictive for tumorigenesis outcome." (PMID 33202721, 2020). "ECM-receptor interaction and focal adhesion pathways were closely related to tumor invasion and metastasis, in which three proteins of ITGA2, COL1A1 and COL11A1 were also behaved up-regulation trend in cancer, except FLNC." (PMID 27626164, 2016). "Transient expression or silencing of filamin C affected the proliferation and colony formation of cancer cells." (PMID 25577646, 2015). "Silencing of endogenous filamin C enhanced cancer cell migration and invasion, whereas ectopic expression of filamin C had opposing effects." (PMID 25577646, 2015). "Data-mining using public microarray datasets shown that filamin C was significantly reduced in many human primary and metastasis cancers." (PMID 25577646, 2015). "It has been shown that the filamin C promoter was frequently methylated in several types of human cancers." (PMID 25577646, 2015). "Taken together, by proteomic analysis of GC cell lines, we identified and characterized a potential tumor suppressor filamin C that was significantly downregulated in GC cell lines and tissues, as well as several other human cancers." (PMID 25577646, 2015). "An in vivo analysis using zebrafish cancer metastasis model demonstrated that reduced filamin C in cancer cells increased cell metastasis." (PMID 25577646, 2015). "We then used a zebrafish cancer metastasis model to investigate the role of filamin C in metastasis of cancer cells in vivo." (PMID 25577646, 2015). "Of these genes, FLNC is particularly interesting since it is frequently repressed at the transcriptional level by promoter methylation in several human cancer types." (PMID 23028731, 2012). "Studies in other tumor types illustrate FLNC’s potential dual role in cancer." (PMID 41373405, 2025). "For instance, FLNC, which is identified as the key mutation of EMT process of BRCA, is crucial in cell contraction and spreading as a large actin-cross-linking protein and is important in the lymph node metastasis of cancers." (PMID 36137089, 2022). "Atsushi Kaneda's study suggested that the methylation of CpG island in the 5′ terminal of FLNC may play an important role in the downregulation of FLNC in the cancer cell." (PMID 27626164, 2016).
cancer (continued). "One of the proteins, FLNC, has been reported to be relevant to cancer." (PMID 27626164, 2016). "While silencing of endogenous filamin C improved cancer cell proliferation and colony formation." (PMID 25577646, 2015). "Based on these results, we hypothesize that filamin C is a potential tumor suppressor that is involved in the initiation and development of GC and other human cancers." (PMID 25577646, 2015). "Filamin C may be a target for the development of novel anticancer drugs for the treatment of GC and other human cancers." (PMID 25577646, 2015). "Finally, our results and findings from other studies suggest that filamin C plays a role in cancer metastasis." (PMID 25577646, 2015). "Therefore, the present study focused on the role of protein filamin C in the development of GC and other human cancers." (PMID 25577646, 2015). "However, knowledge regarding the role of phosphorylated filamin-C in cancers is limited." (PMID 34717622, 2021). "In addition, the mRNA level of filamin C was significantly reduced in a variety of human cancers." (PMID 25577646, 2015). "These experiments suggested that filamin C could inhibit cancer cell proliferation." (PMID 25577646, 2015). "Gene-centric analyses highlight four cancer-relevant loci MAP2K1, FLNC, ABCA1, and TUBB3 as key targets of methylation deregulation, each exhibiting distinct CpG methylation patterns linked to their known biological roles in tumorigenesis." (PMID 41373405, 2025). "Other DSG3-associated cancer-related genes include upregulated OLFM4 (antiapoptotic factor), downregulated ADAMTS1 (antiangiogenic activity), downregulated KRT84 (cancer suppressor in oral SCC) and FLNC." (PMID 38067138, 2023). "FCGBP, FLNC, TLR7, and CSF2RA were potential antigens for developing cancer vaccination, and the patients in IS3 were considered the most suitable for vaccination in LGG." (PMID 34404444, 2021). "The primary molecular abnormality in EBV associated LLC of the stomach is global and non-random CpG island methylation in the promoter region of many cancer-related genes (such as LOX, HRASLS, FLNC, HAND1, and THBD)." (PMID 24188515, 2013). "The significant induction of Filamin C upon treatment with DU145 exosomes observed in LNCaP xenograft bearing mice, provides further evidence to support the role of exosomes in cancer progression and also infer the selective uptake of PCa derived exosomes in vivo by the PCa xenograft tumor." (PMID 26840259, 2016). "Whether downregulation of filamin C is common in other human cancers is not clear." (PMID 25577646, 2015).